INS (insulin)
Diseases named in the same sentence as INS in open-access papers (continued):
Sharing a sentence is not in itself a finding about the gene and the disease.
diabetes (continued). "The rapid onset of diabetes and almost complete loss of insulin production necessitates stu’dies on the progressive inflammatory process in asymptomatic genetically susceptible rats." (PMID 41042382, 2025). "It is known that different races/ethnic groups vary in body composition, insulin sensitivity, susceptibility to diabetes, and the risk of pregnancy-related complications." (PMID 41377936, 2025). "According to the WHO diagnostic criteria for GDM, women diagnosed with diabetes in early pregnancy are more likely to have adverse outcomes and require insulin or other glucose-lowering medications than those generally diagnosed at 24–28 weeks of gestation." (PMID 39752447, 2025). "Physiologically, chronic kidney disease affects 30% of the PwT2D in England, impairing renal clearance of many diabetes medications, such as insulin, metformin and sulfonylureas, which increase the risk of side effects." (PMID 40186412, 2025). "Diabetes mellitus is a serious cause of mortality and a metabolic disorder characterized by hyperglycemia as a result of inadequate insulin production or poor insulin response." (PMID 41346866, 2025). "Pathologic loss of insulin-producing pancreatic β-cells is a hallmark of diabetes that is potentially reversible through regenerative therapy." (PMID 40885390, 2025). "For women, considering that the decline in estrogen levels after menopause can lead to reduced insulin sensitivity, the risk of diabetes for postmenopausal women is 1.42 times higher than that of men." (PMID 40753393, 2025). "Diabetic patients have reduced islet insulin content, potentially underlying the depletion of islet zinc observed in diabetes." (PMID 40885390, 2025). "Elevated CER levels have been linked to impaired insulin sensitivity, inflammation, and oxidative stress, all of which are known to be involved in the development of diabetes." (PMID 41286497, 2025). "Anthocyanins also increase insulin sensitivity, regulate glucose metabolism, and regulate enzymes involved in carbohydrate digestion, thus reducing the risk of diabetes." (PMID 40918166, 2025). "By altering parasympathetic transmission, hypersensitivity to insulin and resistance to its effects—which are frequently linked to aberrant lipid levels and diabetes—have the capacity to cause greater reactivity in the bronchial airways." (PMID 40421215, 2025). "Because of significant weight loss in the AM phenotype, the insulin requirement decreases, the diabetes trajectory decelerates, and CV risk factors decline, including insulin resistance, in a state of a reverse metabolism." (PMID 39852391, 2025). "Higher cumulative estimated glucose disposal rate, reflecting better sustained insulin sensitivity over four years, was associated with a slower nine-year frailty progression among middle-aged and older Chinese adults with diabetes." (PMID 41497955, 2025). "Specifically, lycopene has been found to lower urine and blood glucose levels, increase serum insulin levels, and decrease the risk of diabetes-related pancreatic damage." (PMID 40143179, 2025). "Our study suggests that a short-term LCD intervention significantly improves GV in hospitalized patients with insulin-deficient diabetes, especially those with lower C-peptide levels." (PMID 41586239, 2025). "Dietary patterns profoundly influence insulin sensitivity and inflammatory pathways, shaping the progression of pre-diabetes and health outcomes for those at risk for T1D." (PMID 39860389, 2025). "Thyroid hormones (THs) play essential roles in systemic glucose homeostasis, with clinical evidence indicating that low circulating TH levels correlate with increased diabetes risk through direct modulation of pancreatic β-cell function and insulin secretion." (PMID 41008194, 2025). "Even modest reductions in HOMA-IR can contribute to better insulin sensitivity, potentially reducing the risk of developing type 2 diabetes mellitus over time." (PMID 40018272, 2025).
diabetes (continued). "Increased ghrelin signaling in STZ-DM rats, combined with decreased circulating insulin and leptin, activates hypothalamic neuropeptide responses underlying increased food intake in diabetes." (PMID 41195415, 2025). "Metabolic disorders, notably diabetes mellitus and insulin resistance, were also associated, possibly through the modulation of insulin signaling pathways." (PMID 40732226, 2025). "Diabetes is a chronic disease caused by an absolute or relative insufficiency of insulin secretion and an impairment in its use, and type 2 diabetes mellitus (T2DM) accounted for 90% of all the prevalence." (PMID 39831602, 2025). "Chronic IL-6 activation has been linked to pancreatic beta-cell dysfunction and apoptosis, further impairing insulin secretion and increasing the risk of diabetes progression." (PMID 40142617, 2025). "The HDF Strength(RMS)L-S(%) values were significantly associated with Diabetes duration, Insulin, the LV- myo-LGE(%) and myocardial strain (r = 0.355, p = 0.004; r = 0.305, p = 0.015; r = 0.531, p = 0.006; r = −0.258, p = 0.041)." (PMID 39957999, 2025). "GLUT4 deficiency skeletal muscle is implicated in impaired insulin-stimulated glycogen synthesis in patients with diabetes." (PMID 41154746, 2025). "Impaired insulin function, higher fasting glucose, and increased diabetes risk have also been observed in individuals with anxiety and depression." (PMID 39980848, 2025). "Insulin resistance is closely associated with inflammation in diabetes, and anthocyanins have been implicated in enhancing insulin action." (PMID 39136514, 2025). "This was expected in diabetes, the occurrence of hyperglycemia is caused by deficient production of insulin and insulin resistance." (PMID 38384655, 2024). "Compared with other diabetes medications, insulin was associated with the highest rate of therapeutic errors reported to PCs in this study (starting in 2002), although previous research indicates that most of these incidents can be managed at home." (PMID 39300573, 2024). "Diabetes mellitus (DM) is a chronic metabolic disorder caused by either failure of pancreatic beta cells to produce an insulin or tissue resistance to use insulin or both." (PMID 38439761, 2024). "Other factors such as young age, long diabetes duration, high baseline HbA1c, and insulin treatment were associated with uncontrolled diabetes at 3 years after the survey." (PMID 38448443, 2024). "Magnesium supplementation improves glucose uptake in individuals with diabetes and improves insulin sensitivity markers for those with a heightened risk of developing elevated blood glucose." (PMID 39203767, 2024). "This study examined diabetes-related KAP in individuals who have been previously reported to be at a higher risk of blindness such as those on insulin treatment or with a longer (>6 years) duration of diabetes in Bangladesh." (PMID 39587498, 2024). "Although the pathogenic mechanisms of T1DM and T2DM are different, glucose-lowering treatments such as insulin administration are the common leading cause of hypoglycemia events in patients with both diabetes subtypes." (PMID 38801705, 2024). "Diabetes mellitus is defined as a group of metabolic diseases characterized by chronic hyperglycemia caused by insufficient insulin action." (PMID 39513056, 2024). "The most common type of insulin, type 2 diabetes mellitus, has been caused by inadequate compensatory mechanisms for insulin sensitivity and insulin secretion." (PMID 38236900, 2024). "By analogy with findings in lower animals, some of the diabetic complications and diseases highly associated with diabetes have been thought to be caused by excessive insulin action." (PMID 39513056, 2024). "The term “treatment-induced neuropathy of diabetes” (TIND) has been used in the literature to describe the burning, lancinating pain associated with the initiation of insulin therapy in patients with diabetes." (PMID 38983905, 2024).
diabetes (continued). "It is unsurprising then, that short sleep has also been associated with incident diabetes mellitus, as well as the worsening of markers of insulin regulation." (PMID 38673503, 2024). "Extracellular Ca2+ cannot flow inward and insulin cannot be secreted normally by β cells, which causes diabetes." (PMID 38095268, 2024). "Diabetes mellitus (DM) is a heterogeneous metabolic disorder characterized by a chronic hyperglycemia status; a physiologically abnormal condition caused by disturbed insulin secretion, insulin effect, or both." (PMID 39199200, 2024). "Melatonin treatment improved diabetes in experimental models by regulating the metabolism of body lipid and glucose, decreasing the cell resistance to insulin which causes more insulin sensitivity." (PMID 39011437, 2024). "Reduce markers of systemic inflammation.Increased basal metabolic rate.Improved lipid profiles.Lower body fat percentage.Improved insulin sensitivity and glucose homeostasis.Reduces the risk of obesity-related conditions.Reduces risk of diabetes mellitus." (PMID 39835188, 2024). "Subsequent research has unveiled that diabetes and its ensuing complications, including hyperglycemia, hypoglycemia, and insulin metabolic dysregulation, exhibit a close association with CRCI." (PMID 38914627, 2024). "Diabetes, characterized by either deficiency of insulin secretion, is a widespread chronic condition." (PMID 38665371, 2024). "An alteration of the insulin response, as seen in insulin resistance or diabetes, can cause the loss of the metabolic flexibility that characterizes cardiac cells, potentially causing the development of diabetic cardiomyopathy." (PMID 39125765, 2024). "The genes altered in expression in insulin resistance extended well beyond genes typically linked to insulin action but did include a number that have been previously linked to diabetes." (PMID 38032738, 2024). "For two of the five patients with diabetes requiring insulin, this large weight fluctuation was associated with hypoglycemia and the need to eventually cease insulin." (PMID 38392055, 2024). "Another possible explanation is that insulin users in population of this study were younger at diabetes onset and had higher HbA1c concentrations (independent risk factors for adverse cardiovascular events) relative to non-users." (PMID 38263010, 2024). "Diabetes is a well-known risk factor for CVDs, inducing microvascular and macrovascular complications, and insulin metabolism and endothelial function exhibit interactions." (PMID 38892574, 2024). "Diabetes mellitus is an endocrine disorder that is characterized by hyperglycaemia, which is caused by a deficiency in insulin secretion, insulin resistance, or a combination of both." (PMID 39275349, 2024). "Diabetes is defined by persistent hyperglycemia caused by impaired production or sensing of insulin." (PMID 38918575, 2024). "The B7-H4 protein is expressed and colocalized with insulin, and its polymorphism influences the prevalence of diabetes." (PMID 39571901, 2024). "The amount of reduction of insulin dose should be determined on an individual basis based on prior diabetes control, risk of hypoglycemia and ketosis, type of GLP-1RA started, among others." (PMID 39906033, 2024). "The primary causes of high blood sugar in individuals with diabetes are reduced insulin secretion by the beta-cells in the pancreas and reduced insulin sensitivity in the liver and muscle cells." (PMID 38302935, 2024). "Blood glucose level serves as a crucial diagnostic marker for diabetes, and INS secretion is regulated by the concentration of blood glucose." (PMID 38633528, 2024). "In summary, TyG-BMI is a reliable surrogate marker for IR, and an elevated TyG-BMI indicates decreased insulin sensitivity, thereby increasing the risk of diabetes and various other chronic diseases or adverse outcomes." (PMID 38459527, 2024).
diabetes (continued). "The primary objective of treating diabetes in particular novel pharmacological options leading to significant weight loss is to enhance insulin sensitivity and beta-cell function and subsequently glycaemic control." (PMID 38579770, 2024). "Circulating levels of PEDF are elevated in various metabolic disorders, such as obesity and diabetes, and declined upon weight loss and insulin sensitization." (PMID 38375199, 2024). "Our results were consistent with the previous studies that diabetes duration was negatively associated with residual β-cell function and that autoantibody positivity was correlated with sustained intrinsic insulin production." (PMID 38405156, 2024). "It would have been of interest to have tested for antibodies associated with type 1 diabetes mellitus (eg, insulin autoantibodies, islet cell cytoplasmic antibodies)." (PMID 37758506, 2024). "Considering diabetes is the leading cause of PN, the microneedles in our array are equally or more comfortable to use than the insulin syringes and lancets that these patients are used to receiving." (PMID 39867474, 2024). "There are two main types of diabetes such as type 1 diabetes mellitus, which is caused by a deficiency of insulin production by the pancreas and type 2 diabetes mellitus, which is characterized by insulin resistance despite sufficient insulin production." (PMID 39484638, 2024). "These proteins, including newly identified ones like β-glucuronidase and plexin-B2, are linked not only to diabetes risk but also to key physiological indices such as insulin sensitivity index, acute insulin response, and glucose effectiveness." (PMID 39371930, 2024). "Semaglutide is an anti-diabetes and weight loss drug that decreases food intake, slows gastric emptying, and increases insulin secretion." (PMID 38315575, 2024). "In type 2 diabetes mellitus, because of increased insulin resistance and physiological PI-3/Akt pathway deficiency, the MAPK pathway predominates, with a proatherogenic effect." (PMID 38921685, 2024). "Obesity is associated with alterations in circulating IGF1, IGF1-binding proteins (IGFBPs), insulin, inflammatory markers, and hormones implicated in cardiovascular disease, diabetes, cancer, and aging." (PMID 39458471, 2024). "In particular, Abdalla highlighted a possible link between diabetes and an increased risk of developing AD, which is associated with the protective role of insulin in brain function." (PMID 39273520, 2024). "For example, an As-induced increase in LPS can activate Toll-like receptors (TLR) 4 and 2 and LPS receptor CD14, leading to increased activation of inflammatory pathways; such activation then causes impairment of insulin signaling, which can lead to diabetes." (PMID 39135557, 2024). "Previous research suggests that the dietary fiber in the DASH diet can lower blood glucose levels and enhance insulin sensitivity, thereby reducing the risk of diabetes." (PMID 39737149, 2024). "Diabetes is a collection of metabolic conditions distinguished by high blood glucose levels arising from impairments in insulin secretion, insulin activity, or both." (PMID 39251935, 2024). "Diabetes mellitus is a metabolic disorder that causes chronic hyperglycemia by destroying pancreatic beta cells and impairing insulin-mediated metabolism." (PMID 38881175, 2024). "These two conditions are often present prior to type 2 diabetes mellitus and are linked to moderate insulin resistance in the insulin-dependent tissues." (PMID 39590330, 2024). "This study has shown that compared to white or Hispanic people, black people had reduced insulin sensitivity, and diabetes complications were associated with lower eGDR." (PMID 39768947, 2024). "Over time, this disruption can result in reduced insulin sensitivity and elevated blood glucose levels, heightening the risk of developing diabetes." (PMID 39149550, 2024).
diabetes (continued). "Maternal weight also displayed a positive correlation with milk leptin levels, and maternal diabetes status was positively associated with milk insulin concentrations." (PMID 39021603, 2024). "Diabetes mellitus, a chronic metabolic disorder characterized by hyperglycemia, results from a deficiency in insulin secretion, impaired insulin action, or a combination of both." (PMID 38534414, 2024). "By enhancing insulin sensitivity and improving glucose metabolism, BCAAs help prevent obesity and diabetes, which are major risk factors for GC." (PMID 39634548, 2024). "This oxidative imbalance can trigger apoptosis in β-cells, resulting in a progressive loss of β-cell function and population, inadequate insulin secretion, and ultimately an accelerated progression of diabetes." (PMID 39202492, 2024). "The fundamental characteristics of diabetes include continuous hyperglycemia, gradual weight loss, and insulin dysfunction." (PMID 39479615, 2024). "In contrast to the role of TYK2 in autoimmune T1D described in this paper, we reported that reduced TYK2 expression was a risk factor for β-cell tropic virus-induced diabetes and impaired insulin secretion." (PMID 38351043, 2024). "β-cell specific PTEN-knockout mice were reported to have increased insulin signaling in β-cells and were protected against glucose intolerance induced by high fat diet and diabetes induced by leptin receptor deficiency or streptozotocin." (PMID 38578954, 2024). "The high activity of insulin is a risk factor for all-cause death as demonstrated in the United Kingdom Prospective Diabetes Study (UKPDS) clinical trial for insulin therapy of T2DM." (PMID 39873003, 2024). "Such a loss of LSEC fenestrations can hinder insulin and lipoprotein transport, leading to hepatic insulin resistance, reduced clearance of insulin, diabetes, dyslipidemia, and atherosclerosis." (PMID 39201792, 2024). "While the frequency of hypoglycaemic events leading to hospitalisation in older adults with diabetes seems to have decreased, the medications associated with such hospitalisations remain consistent: insulin and sulfonylureas." (PMID 38256662, 2024). "Diabetes occurs because of deficiency of insulin production from the pancreas, the cells cannot use insulin (insulin resistance), or combination of these." (PMID 39065641, 2024). "Diabetes mellitus (DM) is a disease of abnormal carbohydrate metabolism characterized by hyperglycemia and associated with a relative or absolute impairment in insulin action, along with varying degrees of peripheral insulin resistance." (PMID 39480896, 2024). "The hallmark features of diabetes mellitus include hyperglycemia, insulin resistance, and a relative deficiency in insulin." (PMID 39771551, 2024). "Overall, insulin degludec was deemed to provide a clinically beneficial and patient-friendly option for managing diabetes, addressing many of the challenges associated with basal insulin therapy." (PMID 39766270, 2024). "Diabetes mellitus is a major health problem worldwide and is characterized by deficiency in insulin secretion and/or insulin action." (PMID 38592298, 2024). "TNF-α and IL-6 have been associated with impaired intracellular insulin signalling, potentially leading to insulin resistance and further diabetes complications." (PMID 38614881, 2024). "The duration of diabetes and insulin use are associated with a higher risk of AF and an elevated thromboembolic risk in patients with AF." (PMID 38172896, 2024). "G_Coprococcus has a beneficial effect on the prevention of diabetes, which was positively associated with insulin sensitivity but negatively associated with the presence of dysglycaemia." (PMID 38562415, 2024). "This study highlights the significant financial burden that people with T1D face in the absence of full healthcare coverage and associated rationing of insulin and other diabetes supplies." (PMID 38711747, 2024).